SHH (sonic hedgehog signaling molecule)
Diseases named in the same sentence as SHH in open-access papers (continued):
Sharing a sentence is not in itself a finding about the gene and the disease.
tumor (continued). "Finally, immunohistochemistry (IHC) experiments confirmed the differential expression patterns of the SHH, WDR72, and EPOP genes between tumor and normal tissues, corroborating our findings at the mRNA level." (PMID 41425595, 2025). "Independent of tumor characteristics, such as histology and grades, higher expressions of SHH, PTCH1, PTCH2, and GLI1 have shown beneficial prognostic influence, whereas GLI2, GLI3, and SUFU are correlated with adverse clinical outcomes in OC patients." (PMID 40565349, 2025). "RT‐qPCR and Western blot analyses showed that miR‐217 and TSHZ2 expressions were significantly increased in the tumor tissues of the Lv‐miR‐217 + oe‐NC group compared to the Lv‐NC + oe‐NC group, whereas DNMT1, SHH, and GLI1 expression were significantly decreased." (PMID 40909350, 2025). "Unlike WNT-MB, most SHH-MB patients are newborns or adults; just a few youngsters have this tumor subtype." (PMID 38391759, 2024). "GLI1 is a key transcription factor in the SHH pathway, and H. pylori infection reduces the methylation level of the GLI1 promoter region in an m6A-dependent manner, thereby activating the expression of GLI1 and promoting tumor proliferation." (PMID 39434880, 2024). "Moreover, truncated GLI1 (TGLI1), a product of SHH signalling, functions as an enhanced GLI1, promoting angiogenic heparanase expression and thereby facilitating GBM angiogenesis and tumour growth." (PMID 39568072, 2024). "MB had less inflammation than other tumor types (median TIS = 6.58; p = 0.0002 vs. normal brain), although SHH-subgroup MB had higher inflammation than other MB subtypes (median TIS = 7.72; p = 0.01 vs WNT, p = 0.007 vs Group 3, p = 0.004 vs. Group 4), which is consistent with several prior reports." (PMID 38987542, 2024). "We achieve this by summarizing the intricate crosstalk between the primary c-MET and Hh pathways within tumor cells, the downstream effects of Hh pathway activation on the TME and CAFs, and the role of SHH and HGF serves as a bridge in the context of stromal-tumor interactions." (PMID 37919751, 2023). "In Sonic Hedgehog (SHH)-subgroup MB, OLIG2-expressing tumor stem cells drive recurrence." (PMID 37333134, 2023). "D12M Shh KO cells and tumors showed marked reduction in SHH expression and a similar response to sonidegib as lenti-control tumors suggesting that SHH secretion from stromal cells, not tumor cells, drives Hh pathway activation in osteosarcoma." (PMID 37845394, 2023). "Thus, to get further insights on putative cells of origin of the CAL SHH ATRT, we performed scRNAseq on four fresh human tumor specimens." (PMID 37863903, 2023). "For correlation analysis of SHH, GLI1 and VEGFA immunoreactivity according to the tumor pathological characteristic and patients’ overall survival we divided patients into groups with clinically early/late, histologically benign/malignant and current state dead/alive." (PMID 37964226, 2023). "Targeting the Sonic hedgehog (SHH)-Smoothened (SMO) signaling axis has also been shown to increase cancer cell proliferation and tumor formation by inhibiting SHH-SMO-mediated activation of the tumor-suppressive phenotype in myofibroblasts." (PMID 37723510, 2023). "Moreover, a directly proportional correlation was observed between SHH and VEGFA immunoreactivity in TNM 3 + 4 and Fuhrman/ISUP/WHO 3 + 4 tumor tissues as well as in samples of patients with shorter survival." (PMID 37964226, 2023). "Mechanistically, SHH can induce epithelial–mesenchymal transition (EMT), matrix metalloproteinase 9 (MMP-9) activity and tumor lymphangiogenesis through the PI3K/Akt pathway, thereby promoting tumor progression and LN metastasis." (PMID 37803421, 2023).
tumor (continued). "Additionally, SHH, GLI1, and SMO overexpression were significantly correlated with tumor recurrence and shorter disease-free survival (DFS)." (PMID 37626893, 2023). "Primary cilia are essential for vertebrate SHH signal transduction and have been shown to play critical roles in cerebellar granule neuron progenitor cell (GNPC) proliferation as well as MB tumor progression and drug resistance." (PMID 37726268, 2023). "Under in vitro conditions, we found that cultured tumor cells, in the absence of a stromal compartment, failed to express BMPs and that this can be overcome under the influence of SHH." (PMID 35902550, 2022). "We found a negative correlation between SHH expression and tumor size, which is opposite to previous studies." (PMID 36294994, 2022). "In TNBC, activation of the HH-GLI pathway can be both canonical and non-canonical, while paracrine secretion of SHH by TNBC cells affects tumor stroma which contributes to tumor growth, invasion, and metastasis." (PMID 36294994, 2022). "However, addition of exogenous SHH to the esophageal adenocarcinoma cell lines increased GLI activity and the combination of vismodegib and everolimus (mTOR antagonist) suppressed tumor growth more than either drug alone in vivo." (PMID 36010600, 2022). "IHH, rather than SHH, was demonstrated to be the critical tumor-suppressive Hh ligand through in vivo CRISPR deletion of IHH that recapitulated the phenotype of 5E1 treatment." (PMID 36010600, 2022). "In addition to palbociclib, a recent study has revealed that THZ-1, a covalent inhibitor of CDK7, antagonizes GLI1 and GLI2 transcription, preventing the growth of SHH-driven MBs and SMO inhibitor-resistant human tumor cell lines in vivo and in vitro." (PMID 35573667, 2022). "Alterations in WNT and SHH signalling form the pathogenetic basis for their subgroups, whereas those for non-WNT/non-SHH tumours remain largely elusive." (PMID 35379950, 2022). "Unlike the WNT subgroup, SHH, Group 3 and Group 4 tumours do not show clear subgroup-wide prognostic differences in trials-based cohorts of childhood MBs." (PMID 34885186, 2021). "Besides, the SHH signaling pathway through the MAPK/ERK pathway was found to regulate proliferation, migration and tumor-like behavior of RA FLSs." (PMID 33546769, 2021). "Tumor size, volume, and weight in the sh/LINC01426#1 group were smaller than those in the sh/Ctrl group, whereas, all those indexes were amplified in the sh/LINC01426#1+SHH group." (PMID 33568633, 2021). "However, we noticed that although ABAT expression is decreased in MB compared with normal cerebellum, rare ABAT-expressing cells are found among the tumor bulk and less aggressive MB subtypes WNT and SHH express higher ABAT levels." (PMID 34192534, 2021). "Indeed, among several cytokines that regulate the tumor-bone interaction and were upregulated significantly more by KLF5KQ than by KLF5KR (SHH, WNT5A, IL11, and IL6), the induction of IL-11 was dependent on CXCR4 expression." (PMID 33731701, 2021). "In most available adult studies, a predominance of non-WNT/non-SHH tumours (~60% and almost exclusively Group 4), followed by SHH-activated tumours (~30%), and very rarely WNT-activated tumours (~10%) has been reported." (PMID 34436037, 2021). "Cyclopamine (Cyp, a well‐known inhibitor of SHH signaling pathway) and chloroquine (CQ, the pharmaceutical inhibitor of autophagy) were used in vivo and in vitro (autophagic flux, CCK‐8 assay, wound healing assay, transwell assay, tumor xenograft model)." (PMID 34076346, 2021). "Hh signaling molecules, such as ligands (SHh), receptors (PTCH1) or transcription factors (GLI1/2) in the tumor tissue or body fluid, may reflect tumor progression, metastasis, drug sensitivity or treatment response." (PMID 33440657, 2021).
tumor (continued). "Aberrant activation of the SHH/GLI signaling pathway was also discovered in GBM and was reported to be mediated by truncated GLI 1 (tGLI1) with gain of function, playing a central role in glioma pathogenesis and tumor progression." (PMID 34068501, 2021). "Tumour cells have been described to directly modulate CAF function though secretion of SHH, LIF, TGFβ and IL114,17,29,30, however, it is less clear whether other cell populations in the TME, beyond the tumour cells, can regulate CAF function." (PMID 34921158, 2021). "Plasma and tumor tissue samples from immune checkpoint inhibitor (pembrolizumab and nivolumab)-treated NSCLC patients revealed elevated levels of Wnt and SHH in plasma as well as increased GLI2 levels, suggesting HH and Wnt activation was correlated with immune therapy resistance." (PMID 34831357, 2021). "Taken together, the results of the co-culture and autocrine experiments suggested that SHH from LAD cells activate the pathway in stromal cells in a paracrine manner without autocrine activation in tumor cells." (PMID 32108165, 2020). "As we demonstrated that the intrinsic activation of SHH signaling was mainly due to Gli1 overexpression in response to EWS-FLI1, we then assessed the effects of the specific Gli inhibitor GANT61 on primary ES tumor growth." (PMID 33228057, 2020). "However, canonical SMO-dependent SHH signaling, as mediated by GLI1 nuclear localization, downregulates WNT signaling and tumor cell differentiation." (PMID 31979397, 2020). "Moreover, the treatment (ATO + irradiation) was already explored in one cerebellar HGNET-BCO SHH+/GLI+ tumor, that achieved six-months tumor remission with therapy’s proper safety and tolerability." (PMID 32321992, 2020). "The identification of Cyclin B1 sequestration by PTCH1 demonstrates a tumor-suppressive function independent of downstream SHH signaling components." (PMID 32957513, 2020). "In GBM and other tumor types, where the SHH pathway presents an important role for GSC maintenance, the targeting of SHH in combination with other drugs might be more suitable, as has been demonstrated in vitro and in vivo." (PMID 32722427, 2020). "Specifically, tumor cells with mutant KRASG12D communicate with PSCs via SHH signaling, which is transduced by PSCs, but not by KRASG12D PDAC cells." (PMID 32752017, 2020). "Similarly, another study also found that NC reduced tumor volume and tumor weight in mice via suppression of ERK, STAT3, and SHH pathways, and regulation of Bcl-2, Bax, CyclinD1, VEGF pathway." (PMID 31956371, 2020). "Loss of IHH, another Hh ligand, by in vivo CRISPR led to more aggressive tumor growth suggesting that IHH, rather than SHH, activates the pathway in stroma to drive its tumor suppressive effects—a novel role for IHH in the lung." (PMID 32108165, 2020). "In medulloblastoma, tumor derived Sonic hedgehog (SHH) induces PlGF production in the cerebellar stroma, which promotes tumor cell survival through NRP1 independent of VEGFR1." (PMID 30717262, 2019). "Pathway analysis of the tumor revealed activation of the sonic hedgehog (SHH), the wingless and integrated-1 (WNT), the IGF, and the Notch pathway." (PMID 31480400, 2019). "To evaluate if the targeting of the SHH and the IGF1R pathway could affect the growth of the tumor and to prioritize related drugs, we tested the effect of relevant drugs on the tumor cells (225ZL) isolated from the first relapse of the patient." (PMID 31480400, 2019). "In contrast to WNT-MB, SHH-MB displays a BBB, which seems to be induced by tumor cells." (PMID 31700613, 2019). "The expression of PTCH in tumor blood vessels also showed the same tendency as the expression of SHH, and PTCH was not expressed in blood vessels in the connective tissue adjacent to the non-cancerous region epithelium." (PMID 31744214, 2019).
tumor (continued). "In the expansion phase of CGNPs in the cerebellum, SHH and IGF are required, and it has been suggested that the activation of both pathways in CGNPs could interact and enhance tumor formation in the cerebellum." (PMID 29932116, 2018). "SHh/Gli signaling plays an important role in solid malignancies; downstream pathway effectors are tied to EMT, and many serve as potential therapeutic targets in the prevention of tumor aggression and metastasis." (PMID 29416661, 2018). "In addition, it has been reported that the higher the activation of SHH signaling, the more the neoplasia resemble human BCC, while with lower SHH activation the tumors are more hair-follicle-like." (PMID 29301290, 2018). "In the case of mouse MB, the absence of the tumour microenvironment, specifically astrocytes that secrete SHH, was not present in the cell culture conditions employed." (PMID 30068568, 2018). "Extrapolation of this observation to human type 2 medulloblastomas would imply that deregulation of SHH signalling does not require more than normal OTX2 levels to ensure tumour cell proliferation." (PMID 30100614, 2018). "These trials demonstrated that SHH blockade reduced desmoplasia and increased tumor perfusion in a subset of patients, but these changes did not correlate with patient survival." (PMID 30108679, 2018). "Besides, a growing body of evidence points to the SHH signaling pathway as being the responsible for promoting the activity of mTORC1/4E-BP1-dependent translation and enhance tumor formation." (PMID 29932116, 2018). "We examined the expression of Gli1and Patched regulated by SHH signaling in tumor samples after treatment in the presence or absence of GDC-0449." (PMID 29042665, 2017). "Three tumours were not analyzed by NanoString method due to the lack of RNA but they belonged to non-WNT/SHH type (Group 3 or 4)." (PMID 28376765, 2017). "For example, SHH knockdown by siRNA in OSCC SAS cells failed to induce tumor angiogenesis and tumor growth when it was subcutaneously xenografted in mice." (PMID 28708091, 2017). "As we find that CDON is expressed in the tumour cell compartment, this leaves a possible tumour-promoting role for a non-canonical SHH/CDON/PTCH1 axis, acting independently of downstream Hh signalling." (PMID 27492255, 2016). "Surprisingly, SHH was expressed only in a minority of tumor biospies and not at all in adherent cell lines, sphere cultures, xenografts or murine skeletal muscle." (PMID 26189795, 2016). "By whole transcriptome sequencing and Ingenuity Pathway Analysis, we identified the activation of the Sonic Hedgehog (SHH) and of the WNT signaling pathway in two different regions of the primary tumor and of one inoculation metastasis compared to normal brain." (PMID 27825128, 2016). "However, when screened in conjunction with heterotypic stromal cells, our study additionally identified SHH, AKT, and IGF1R/AXL inhibitors as KRASG12D-dependent targets in tumor cells." (PMID 27087446, 2016). "SHH protein expression was significantly higher in tumor tissue compared with that in non-tumor tissue (P = 0.013)." (PMID 27039174, 2016). "Comparing papCP and adaCP tumor samples, the latter showed significant up-regulation of direct targets of the Wnt/β-catenin signaling pathway (LEF1 and AXIN2) as well as important components of the hedgehog signaling pathway (GLI2, PTCH1 and SHH)." (PMID 26927026, 2016). "SHH-mediated GLI1 activity lead to the transcriptional activation of the cysteine-rich angiogenic inducer 61 (CYR61); silencing CYR61 resulted in reduced tumor vasculature of SHH-driven xenografts." (PMID 26988232, 2016). "In vitro analysis showed that most LAC cell lines did not express significantly enhanced SHH or GLI1 than non-tumor lung epithelial cells, but had a remarkably reduced HHIP expression." (PMID 27015549, 2016). "In this study, Gli-2 was barely expressed in tumor cells, suggesting that a high level of the ligand SHH can not respond to it in an autocrine fashion." (PMID 27007126, 2016).
tumor (continued). "SHH (sonic hedgehog homolog) was shown to be highly expressed (FC = 96.9, p = 1.5 × 10−48) by ACP in this study, which is consistent with a recently developed mouse model of ACP and is the focus of oncology drug development for a number of tumor types." (PMID 25990246, 2015). "Targeting the stroma by adding the SHH inhibitor, CUR199691, to the treatment regimen increased drug delivery 10-fold, prolonged progression free survival of the treated mice, and depleted the CSC subpopulation in the tumor remnants." (PMID 25337831, 2014). "Oncogenic KRAS activates SHH production, but HH ligands do not activate the HH pathway in tumor epithelial cells in an autocrine manner (Lauthet al., 2010;Millset al., 2013;Yauchet al., 2008)." (PMID 25352983, 2014). "Furthermore, Chaudary and colleagues correlated the gene expression of different Hh components (SHH, IHH, PTCH1, PTCH2, GLI1) with clinicopathological data (tumor hypoxia, local recurrence and DFS) from cervical adenocarcinoma samples after CRT." (PMID 23880852, 2013). "Once again, our primary tumor specimens demonstrate very little to no expression of SHH transcript when compared to a positive control expressing SHH cDNA." (PMID 19859563, 2009). "Our earlier data from NIH3T3 indicated little or no expression of Sonic Hedgehog (SHH), which mediates pathway activity in development and in some tumor systems." (PMID 19859563, 2009). "PCR also showed that normal tissues had low or no level of SHH expression, while tumor tissues had elevated RNA level of SHH." (PMID 19943941, 2009). "Our results show that the SHH signaling pathway promotes tumor cell growth in human CRCC, regardless of the VHL status." (PMID 20015350, 2009). "Our independent IHC experiments further confirmed that the IHC scores of SHH (4.56 ± 1.46 vs. 2.16 ± 0.79, p < 0.0001), EPOP (4.91 ± 1.76 vs. 2.84 ± 1.05, p < 0.0001), and WDR72 (4.73 ± 2.03 vs. 2.91 ± 2.15, p < 0.01) were significantly greater in tumor tissues than in normal tissues." (PMID 41425595, 2025). "Mice lacking the SHh gene developed tumours with a smaller stroma and had fewer activated PSCs." (PMID 41561521, 2025). "This may predict the lack of efficacy of SHH-targeting compounds in curtailing tumor growth but could instead significantly impede cerebellar development." (PMID 39835775, 2025). "This World Health Organization (WHO) grade IV neoplasm arises from impaired developmental processes affecting cerebellar and brainstem precursor cells during human embryogenesis, involving activation of the WNT and Sonic Hedgehog (SHH) signaling pathways and amplification of MYC and MYCN oncogenes." (PMID 40805120, 2025). "For example, SHH signalling exhibits heightened activity in PDAC, inducing insulin growth factor 1 (IF1) and growth arrest-specific (GAS6) expression, both activating Akt signalling in the tumor cell, leading to increased cell proliferation and resistance to apoptosis." (PMID 38540204, 2024). "WNT, SHH, and Group D (later reclassified as Group 4), with an absence of Group 3 tumours." (PMID 38396397, 2024). "In their investigation using irradiated non-tumor cells, Leonard J.M. found that SHH signaling, when improperly activated, could exacerbate the effects of radiation on genomic instability and subsequent tumor progression." (PMID 38730691, 2024). "When tumor cells are co-cultured with macrophages, the presence of CCA cells increases the proportion of M2-polarized TAMs and the level of transforming growth factor beta 1 (TGF-β1) secreted by TAMs, while downregulation of SHH expression reverses these increases." (PMID 39290697, 2024). "Interestingly, GLI1, a transcription factor previously thought to be critical for SHH-induced tumourigenesis, was found to be non-essential for tumour formation, as MBs developed even in GLI1 null mutant mice." (PMID 39568072, 2024).